BDNF (brain derived neurotrophic factor)
Diseases named in the same sentence as BDNF in open-access papers (continued):
Sharing a sentence is not in itself a finding about the gene and the disease.
Obesity (continued). "Many studies using HFD-induced obesity mouse models have also documented the increased inflammation, insulin resistance, and reduced BDNF level in the hippocampus." (PMID 35745162, 2022). "Haploinsufficiency in human BDNF is negatively correlated with obesity, which emphasizes the pivotal role of BDNF in energy homeostasis regulation." (PMID 35626286, 2022). "Rodent models of obesity exhibit a downregulation of BDNF with consequent impairment of cognitive function, especially in the hippocampus where BDNF’s contribution to synaptic plasticity and memory processes is prominent." (PMID 35761012, 2022). "The disruption of one copy of the BDNF gene as consequence of chromosomal rearrangement was described in a child affected by severe obesity and several cognitive alterations." (PMID 36452324, 2022). "They analyzed the five obesity-associated genetic variants (MC4R rs17782313, BDNF rs6265, FTO rs1421085, TMEM18 rs7561317, and NEGR1 rs2815752)." (PMID 35627568, 2022). "Of these genes, brain-derived neurotrophic factor (BDNF), a growth factor essential for neuronal development and synaptic function, contributes to obesity." (PMID 35338053, 2022). "BDNF activity is also negatively correlated with insulin resistance, obesity and blood glucose levels." (PMID 35408868, 2022). "The ROC curves for obesity prediction on the BDNF of a case-control study on school children expressed a prediction value above 0.65 in two different models." (PMID 35626286, 2022). "Numerous studies have recommended the role of BDNF (rs6265) in the progression of obesity or a significant increase in BMI." (PMID 36742047, 2022). "Similar findings have been shown in mice where reduced BDNF expression, either due to a brain specific conditional knockout or due to heterozygous gene expression, leads to hyperphagia, obesity, and insulin and leptin resistance." (PMID 35225959, 2022). "Albiflorin has antidepressant-like effects by increasing hippocampal expression of 5-hydroxytryptamine (5-HT)/norepinephrine (NE) and brain-derived neurotrophic factor (BDNF) and also ameliorates obesity by modulating the expression of thermogenic genes." (PMID 35529925, 2022). "Heterozygous BDNF knockout mice had reduced BDNF expression which led to age-dependent obesity and an insulin-resistant phenotype, and were characterised by elevated circulating levels of insulin, leptin and glucose." (PMID 36008755, 2022). "Another symptom of SINO is obesity, and indeed the CaMKII-Cre-driven deletion of BDNF induces obesity." (PMID 35140204, 2022). "More recently, we found that PVH-specific overexpression of brain-derived neurotrophic factor (Bdnf), one of Rai1’s direct target genes, during early adolescence was sufficient to fully rescue obesity in SMS mice." (PMID 36410433, 2022). "Lower levels of circulating BDNF increase food intake, weight gain, and adiposity, and hence can be considered a genetic determinant of obesity or IBMI." (PMID 36742047, 2022). "The mean concentration of BDNF in the overweight, obesity class I, II, and III categories were 282.2 pg/mL, 247.9 pg/mL, 186.3 pg/mL, and 178.6 pg/mL, respectively." (PMID 36676721, 2022). "The neuronal BDNF/TrkB axis and its function in adipose tissue play an important role for metabolic regulation and its influence on food intake and obesity." (PMID 35907096, 2022). "High levels of BDNF activity can reduce insulin resistance, obesity and blood glucose levels via the hypothalamic melatonin pathway." (PMID 36358820, 2022). "Previously, it has been shown that hippocampal BDNF and nNOS affect cognitive function, including mood-related behaviors, in obesity." (PMID 36091357, 2022). "For instance, animal studies have shown that knockouts of BDNF induce hyperphagia and obesity, and BDNF administration decreases food intake, increases energy expenditure, and reduces body weight." (PMID 35850718, 2022).
Obesity (continued). "Many case reports have been described with severe hyperphagia, obesity, and cytogenetic deletions of chromosome 11p BDNF gene locus." (PMID 36232301, 2022). "Our data also showed that BDNF levels were significantly lower in people with obesity classes II and III than those of normal weight (p < 0.05)." (PMID 36676721, 2022). "In people with obesity and type 2 diabetes, BDNF is downregulated, which has drawn interest in the research on the central regulation of food intake due to its widespread expression in brain regions implicated in appetite regulation." (PMID 36742047, 2022). "Because the mature BDNF protein levels in the hippocampi of db/db mice were low, it is possible that the proteolytic cleavage of proBDNF is impaired in the CNS in severe obesity." (PMID 36091357, 2022). "Pre-clinical data have shown that central alterations of BDNF signaling in mice results in severe hyperphagia and obesity." (PMID 35911513, 2022). "Emerging evidence shows that oxytocin and BDNF regulate a range of physiological processes, including maternal behavior, cell metabolism, eating behavior, and obesity." (PMID 35721318, 2022). "The index of obesity, such as body weight and serum cholesterol concentration, is related to the brain BDNF." (PMID 35408585, 2022). "WAGR syndrome has been associated with a deletion in the brain-derived neurotrophic factor (BDNF) gene in the chromosome 11p13 region, which leads to the obesity phenotype." (PMID 36232301, 2022). "On the other hand, high-fat diet promotes obesity, depressive-like phenotypes and reduction of BDNF in the hippocampus, a brain region important in controlling the mood." (PMID 35911513, 2022). "Germ-free mice have increased levels of two obesity-suppressing agents: BDNF in the hypothalamus and proglucagon (precursor of glucagon-like peptides—GLP1 and 2) within the digestive system." (PMID 36501063, 2022). "It demonstrated overweight negatively correlated with higher levels of serum tropomyosin receptor kinase B. Hence, we assume brain-derived neurotrophic factor and its high-affinity receptor are responsible for obesity modulation." (PMID 34586159, 2021). "In mice models of diabetes and obesity, BDNF administration produced anorexigenic effects, reduced blood glucose and increased pancreatic insulin content." (PMID 34833132, 2021). "Novel interventions focused on BDNF are being developed for obesity and related metabolic disorders." (PMID 33868169, 2021). "Regarding the level of BDNF in adolescents in this study, serum BDNF levels regulated the relationship between overweight/obesity and EC with an impact of 7.30%." (PMID 33916706, 2021). "BDNF promotes stability of dendritic synapses of the hypothalamic neurons, and it has been shown that neurodevelopmental anomalies involving BDNF contribute to the obesity phenotype." (PMID 34248679, 2021). "We have developed a molecular therapy and demonstrated the efficacy and safety of hypothalamic BDNF gene therapy in diet-induced and genetic models of obesity as well as aging mice of normal weight." (PMID 34394087, 2021). "For future research it would be interesting to include a normal-weight control group to get a better understanding of the relationship between obesity and BDNF." (PMID 35127775, 2021). "Further studies will be required to reveal the interrelationship between the 4 parameters (overweight/obesity, EC, 5-HT and BDNF), and the approach of Preacher and Hayes (2004) was used to test the saliency of the indirect effects." (PMID 33916706, 2021). "The expression of BDNF is negatively correlated with body weight and BMI, which is reduced in patients with obesity and metabolic syndrome." (PMID 33868169, 2021). "Heterozygous BDNF gene knockout mice reduce the gene expression of BDNF, and lead to increased levels of circulating leptin, insulin, and glucose, which are related to weight gain and obesity." (PMID 34482368, 2021).
Obesity (continued). "BDNF involvement in the regulation of energy homeostasis was also reported in humans, in a young patient characterized by the early onset of obesity and hyperphagia along with developmental delays and other neurological defects." (PMID 34833132, 2021). "The BDNF level played a partial mediating role between overweight/obesity and EC that accounted for 7.30% of the total effect value." (PMID 33916706, 2021). "The participation of BDNF in development of obesity and food intake regulation is a controversial issue." (PMID 34586159, 2021). "Previous research has revealed that dietary intakes alter the relationship between BDNF genotype and obesity-related behaviors, which is corroborated by findings in rats." (PMID 34580389, 2021). "The results indicated that the direct effect of overweight/obesity accounted for 83.94%, the mediating effect of 5-HT accounted for 8.76%, and the mediating effect of BDNF accounted for 7.30%." (PMID 33916706, 2021). "Several candidate genes have been identified as being positively associated with BMI and obesity, including the fat mass and obesity associated gene (FTO), and more recently, the brain derived neurotrophic factor (BDNF) gene." (PMID 34867148, 2021). "This highlights the importance to consider BDNF pathways when investigating obesity and obesity treatment." (PMID 33367955, 2021). "The BDNF (rs925946), INSIG2 (rs3771942) and CNR1 (rs6454674) variants are well stablished genetic determinants of obesity." (PMID 34683180, 2021). "The present study revealed a significant positive correlation between plasma BDNF levels and visual food cue-reactivity in the bilateral insulae in patients suffering from obesity." (PMID 33367955, 2021). "Nevertheless, numerous studies have reported the influence of BDNF levels in different health-based outcomes, such as obesity, autism, cognitive function and attention deficit-hyperactivity disorder." (PMID 33662047, 2021). "On the effect of diet on the BDNF serum, some nutrigenomic studies have done based on diet or other macronutrient induced obesity and healthy diet." (PMID 34580389, 2021). "In fact, deletions inducing haploinsufficiency of BDNF were suggested to result in severe obesity in mice." (PMID 33367955, 2021). "Brain-derived neurotrophic factor has been shown to play an integral role in regulating appetite in both humans and animals, and exogenous administration of BDNF has hypophagic effects, while BDNF deletion has hyperphagic effects leading to severe obesity." (PMID 34867148, 2021). "We constructed a genetic risk score (GRS) based on five genetic variants (MC4R rs17782313, BDNF rs6265, FTO rs1421085, TMEM18 rs7561317, and NEGR1 rs2815752) and examined its association with obesity-related traits in a sample of Pakistanis." (PMID 33859285, 2021). "Among the 26 participants with a reported BDNF deletion, close to two-thirds reported obesity (n = 17) and close to a third (n = 7/22) reported obesity with short stature." (PMID 34970513, 2021). "There is also evidence that BDNF plays a role in regulation of appetite and result in a phenotype of hyperphagia and obesity." (PMID 34525971, 2021). "BDNF play important role in etiology of diabetes and obesity by probably biological mechanism including controlling food behaviour, energy homeostasis and anorexigenic effects." (PMID 34580389, 2021). "Firstly, despite the study included a large sample size, it only covers the effects of overweight/obesity on serum 5-HT and BDNF levels as well as the EC response in young and fit healthy adults." (PMID 33916706, 2021). "In the model, 5-HT and BDNF were defined of the relationship between overweight/obesity and EC as mediators." (PMID 33916706, 2021). "There is increasing evidence that brain-derived neurotrophic factor (BDNF) impacts on the development of obesity." (PMID 33367955, 2021).
Obesity (continued). "Patients suffering from obesity showed a significant positive correlation between plasma BDNF levels and visual food cue-reactivity in the bilateral insulae." (PMID 33367955, 2021). "Next to obesity, BDNF has been linked to obstructive sleep apnea (OSA) and endothelial dysfunction, two obesity-related comorbidities." (PMID 35127775, 2021). "Studies in the general population have significantly shown that BDNF is correlated with appetite regulation, energy homeostasis, and obesity." (PMID 34482368, 2021). "Cai et al33 reported that hippocampal ER stress affects the levels of neuronal plasticity‐related proteins (like BDNF) in rats with HFD‐induced obesity." (PMID 33943005, 2021). "Therefore, it might be hypothesized that the described anorexigenic feedback mechanism associated with BDNF signaling is attenuated in patients suffering from obesity, comparable with the insulin or leptin resistance as a consequence of long-lasting overeating in patients suffering from obesity." (PMID 33367955, 2021). "In conclusion, using a sample drawn from a study of college students, we found that overweight/obesity was related to decreased 5-HT and BDNF, which was itself related to lower EC." (PMID 33916706, 2021). "Overweight/obesity not only affects 5-HT; it also affects BDNF, as suggested by the observation that people with obesity have low circulating levels of BDNF." (PMID 33916706, 2021). "With respect to the specific direct effect of each proposed mediator between overweight/obesity and EC, 5-HT (B = −0.10, p ≤ 0.05) and BDNF (B = −0.11, p ≤ 0.05) were significant." (PMID 33916706, 2021). "The role of BDNF in food intake, appetite, energy homeostasis, and obesity is undisputed; however, the mechanism and mode of action of BDNF in such a complex process is not well understood." (PMID 32272767, 2020). "In this study, we enrolled 78 patients with obesity and evaluated the change of BDNF and FGF21 6 months after LSG." (PMID 32210348, 2020). "Obesity suppresses brain‐derived neurotrophic factor (BDNF) expression and increases the expression of pro‐inflammatory cytokines." (PMID 32681810, 2020). "These two types of exercise intensity have been widely investigated, however, experiments evaluating obesity, cognition and BDNF all together, are still scarce." (PMID 32778721, 2020). "Recently, mature-BDNF was reported to play an essential but intricate role in body weight control, and the impairment in the activation of BDNF-TrkB receptor resulted in increased appetite, reduced energy expenditure, and austere obesity." (PMID 33375318, 2020). "Studies of obesity have also demonstrated effects on major central nervous system biomarkers, such as a decrease in BDNF levels in the hippocampus with reversal of the effect following vitamin D administration." (PMID 32102680, 2020). "Heterozygous BDNF-knockout mice are obese, hyperphagic and hyperactive and disruption and deletion of BDNF have been described in patients with obesity." (PMID 30926952, 2020). "Obesity caused by other genetic mutations in the leptin-melanocortin pathway include proopiomelanocortin (POMC) and melanocortin receptor 4 (MC4R), brain-derived neurotrophic factor (BDNF), and the tyrosine kinase receptor B (NTRK2) genes." (PMID 33511092, 2020). "Lately, many researchers have been interested in the linkage between obesity and adipokines/myokines, particularly adiponectin and brain-derived neurotrophic factor (BDNF)." (PMID 33375318, 2020). "Loss-of-function studies provide further supportive evidence for the systemic functions of BDNF; heterozygosity for Bdnf results in hyperphagia, obesity, and abnormal locomotor activity." (PMID 32655354, 2020). "This study examined the effect of KME ingestion before an oral glucose tolerance test (OGTT) on plasma BDNF in normal-weight adults (NW) and adults with obesity (OB)." (PMID 33013465, 2020).
Obesity (continued). "Since obesity has been characterized by accelerated aging of adipose tissue, we examined pro-BDNF expression levels in 12-week HFD-fed mice." (PMID 32489703, 2020). "Despite these strong correlations between altered function of BDNF and its receptor TrkB with obesity, this growth factor has been predominately studied only in the CNS." (PMID 33297933, 2020). "Overall, treatment with recombinant BDNF was beneficial to treat obesity and diabetes in rodent models." (PMID 32489703, 2020). "The exogenous infusion of BDNF reversed MC4R induced obesity and hyperphagia partially in agouti lethal yellow mice." (PMID 32272767, 2020). "The limitation of this study is that after obesity treatment by high-fat diet induction, BDNF activation and GSK3β inhibition were confirmed by endurance exercise and lithium treatment, but no direct change in brain function was confirmed." (PMID 32397675, 2020). "Recent studies show brain-derived neurotrophic factor (BDNF) and fibroblast growth factor 21 (FGF21) are neurotrophic factors associated with obesity and diabetes mellitus (DM)." (PMID 32210348, 2020). "Based on the results of previous studies, endurance exercise and lithium treatments are expected to have a positive effect on obesity-induced neurodegenerative disorder prevention through BDNF activation and GSK3β inhibition in the hippocampus of obese rats." (PMID 32397675, 2020). "In humans, plasma BDNF is decreased in individuals with both obesity and T2D, and is inversely correlated with serum levels of free fatty acids and insulin resistance." (PMID 31736870, 2019). "This argument is further supported by the fact that exercise that is beneficial in preventing obesity and development of type 2 diabetes enhances the synthesis and secretion of both BDNF and LXA4." (PMID 31823816, 2019). "Deleting BDNF or a BDNF knockdown in the brain or hypothalamus induces hyperphagia and obesity in mice." (PMID 31118969, 2019). "Results coming from animal experiments cited above suggest a great therapeutic potential of training-evoked BDNF in the treatment of obesity." (PMID 31341469, 2019). "According to previous studies, insulin regulates synaptic plasticity in the hippocampus, and HFD-induced obesity reduces hippocampal BDNF levels and neurogenesis, and this leads to impairments in cognitive function." (PMID 31311133, 2019). "Further, researchers have shown that circulating BDNF is lower in individuals with metabolic syndrome, obesity and type II diabetes mellitus (T2DM) when compared to healthy controls." (PMID 31700717, 2019). "Plasma BDNF levels are reduced in subjects with obesity and type 2 DM, though this has been disputed." (PMID 31823816, 2019). "These latter results directly indicated that high levels of BDNF in the hypothalamus evoked by training is effective for the prevention of obesity." (PMID 31341469, 2019). "Conversely, BDNF infusions were able to attenuate or reverse weight gain, hyperglycemia, hyperphagia and obesity." (PMID 31700717, 2019). "Hyperphagia, obesity, reduced satiety and metabolic imbalances have been observed in BDNF deletions, BDNF knockout in rodents, and BDNF haploinsufficiency in humans." (PMID 31700717, 2019). "This is the first study that examined the relationship between neurological markers CNTN2 and BDNF in circulating exosomes with biological predictors for poor neonatal iron endowment, including maternal anemia, obesity, and diabetes." (PMID 31623079, 2019). "A recent meta-analysis confirmed only one BDNF SNP, rs925946, significantly related to obesity and BMI in large groups of healthy subjects." (PMID 30542302, 2018). "In contrast to our study and cited findings, the presence of one or two A alleles of the BDNF Val66Met was significantly associated with lower HDL cholesterol levels and higher risk for obesity in old and very old Chinese healthy subjects." (PMID 30542302, 2018).